TCF19 (transcription factor 19)
Diseases named in the same sentence as TCF19 in open-access papers (continued):
Sharing a sentence is not in itself a finding about the gene and the disease.
tumor (9 papers, 2014 to 2025). "Sen, Yang GH, and Mondal reported that TCF19, a novel pancreatic islet regulator, regulated the processes of energy metabolism and stress adaptation associated with the tumor cells by regulating gluconeogenesis." (PMID 36111242, 2022). "Analysis of tumor samples from patients treated with targeted or checkpoint inhibitors suggests that downregulation of TCF19 is associated with therapy response." (PMID 29650805, 2018). "Moreover, the computational dissection of the tumor microenvironment in the in vivo orthotopic tumors using xCell uncovered endothelial cells as the stromal components exhibiting the most robust direct association with TCF19 perturbation." (PMID 40952912, 2025). "Moreover, TCF19 was significantly associated with the crucial tumor-related marker genes that controlled the various biological processes, including the TGF beta signaling pathway, TNFA signaling, hypoxia, coking death, repair of DNA, autophagy, and ferroptosis." (PMID 36111242, 2022). "Remarkably, TCF19‐depleted cells showed a strong defect in tumor growth that correlated with a reduced primary tumor size and weight at the experimental endpoint." (PMID 40952912, 2025). "Consistent with this notion, our patient data show a tumor and metastasis supportive role for TCF19 in PCa." (PMID 40952912, 2025). "To investigate TCF19’s function in tumorigenesis in vivo, we conducted subcutaneous tumor formation assays using nude mice." (PMID 38579171, 2024). "In contrast, TCF19[T] overexpression was observed to impede tumor progression when compared to TCF19[C]." (PMID 38579171, 2024). "Since TCF19 significantly affects the tumor immune microenvironment, more studies need to be conducted on the immune cells, tumor microenvironment, immunomodulators, and immunotherapy responses to gain in-depth knowledge." (PMID 36111242, 2022). "At the beginning of the research, we identified the expression differences of TCF19 in tumor tissues relative to the normal samples." (PMID 36111242, 2022). "TCF19 is present in almost all human tissues, and its levels of expression are high in various tumor tissues." (PMID 36111242, 2022). "The coexpression analysis method was further used to explore the relationship between the level of TCF19 expression and 33 tumor immune-related genes." (PMID 36111242, 2022). "The prognostic value of TCF19 was determined by analyzing various clinical parameters, such as survival duration, age, the stage of the tumor, and sex of the patients." (PMID 36111242, 2022). "In contrast, co‐targeting BET and MEK led to a striking reduction in tumor volume, improved animal survival, and decreased expression of TCF19." (PMID 29650805, 2018). "Interestingly, the combination of computational, in vitro, and in vivo experimental strategies revealed that, beyond the role of TCF19 in supporting tumor‐intrinsic properties, it also contributes to tumor microenvironment remodeling." (PMID 40952912, 2025). "Therefore, more studies are needed to determine the specific role and mechanism of TCF19 in tumour immune escape." (PMID 38579171, 2024). "They reported that TCF19 could be potentially correlated with tumor prognosis by conducting gene assays, K–M survival analysis, and western-blot tests." (PMID 36111242, 2022). "Additionally, combined BET/MEK inhibition synergistically downregulated TCF19 triggering death of therapy‐resistant tumor cells." (PMID 29650805, 2018). "It is a putative tumour suppressor gene, targeting cell migration and invasion genes, growth genes, cellular adhesion genes and a functionally validated cell cycle progression gene called TCF19 (transcription factor 19)." (PMID 24676469, 2014). "Interestingly, TCF19‐depleted tumors showed an increased level of αSMA around the vessels, suggestive of increased functional pericyte coverage and a potential reduction in vascular permeability that enables tumor cell intravasation." (PMID 40952912, 2025).
tumor (continued). "Recent findings indicate that TCF19, highly expressed in microsatellite unstable (MSI) endometrial carcinoma compared to microsatellite stabilized (MSS) tumors, plays a dual role in tumor progression." (PMID 39161768, 2024). "Furthermore, combined inhibitory therapy targeting TCF19 and PD-1 has been shown to restore CD8 T cell functionality and regain tumor control." (PMID 39161768, 2024). "It is particularly interesting that the TCF19 gene colocalizes with the MHC class I genes, suggesting that the former may relate to tumor immunology." (PMID 29661909, 2018).
infection (2 papers, 2018 to 2023). The state of being infected such as from the introduction of a foreign agent such as serum, vaccine, antigenic substance or organism. "We also found 12 genes associated with infection at six loci, including four infection-specific genes (TCF19, ABO, OBP2B, and TLE1)." (PMID 37886583, 2023). "A group of Treg-signature genes (Areg, Arhpag20, Bub1b, Ccl12, Ccr5, Il1r1, Mki67 (Ki67) Ncf1, Nrp2, Tnfrsf9, Tcf19, Uhrf1, and Wnt3) were expressed at higher levels in IFNARfl/fl x Foxp3YFP-Cre mice than WT controls on day 5 Armstrong infection." (PMID 29672594, 2018).
cardiovascular disease (1 paper, 2025). "The role of ATAD2 and TCF19 in cardiovascular disease was so far unknown." (PMID 40962957, 2025).
neurological diseases (1 paper, 2013). "Remarkably, about 13% of the DEGs in FGF2 treated S252W fibroblasts were associated with neurological diseases (BAT3, HS6ST1, IFI44L, RFC3, RPS9, STRC and TCF19)." (PMID 23593218, 2013). "Seven (12.7%) of the DEGs were associated with neurological diseases (BAT3, HS6ST1, IFI44L, RFC3, RPS9, STRC and TCF19) according to the IPA analysis (p = 0.003)." (PMID 23593218, 2013).
TCF19 also shares sentences with these, for which no sentence is quoted: renal clear cell carcinoma (4 papers); head and neck cancer (3); liver cancer (3); autoimmune thyroiditis (2); cervical cancer (2); cutaneous melanoma (2); oral cancer (2); ulcerative colitis (2); ankylosing spondylitis (1); astrocytoma (1); Autoimmunity (1); chronic hepatitis B (1); Cirrhosis (1); endometrial cancer (1); hypothyroidism (1); immune diseases (1); major depressive disorder (1); metabolic disease (1); metastatic prostate carcinoma (1); myocardial infarction (1); pancreatic cancer (1); psoriasis vulgaris (1); rheumatoid arthritis (1); squamous cell carcinoma (1); thyroiditis (1).